ATM (ATM serine/threonine kinase)
Diseases named in the same sentence as ATM in open-access papers (continued):
Sharing a sentence is not in itself a finding about the gene and the disease.
breast cancer (continued). "In the patients with HER2-low breast cancer, patients with homologous recombination related genes (HRRGs) defects had an HRD score about twice that of those without related genes mutations, and were at higher risk of acquiring ARID1A, ATM, and BRCA2 mutations." (PMID 38366907, 2024). "Germline ATM mutations confer an increased susceptibility to familial breast cancer and are associated with homologous recombination deficiency (HRD) in patients with BRCA1/2-wt breast cancer." (PMID 38539474, 2024). "We found evidence of a statistically significant association with breast cancer risk for three genes, with ORs of 16.3 [95% CI: 4.0–66.7] (p = 0.0001) for BRCA1, 12.0 [95% CI: 2.9–45.9] for BRCA2 (p = 0.0001), and 7.3 [95% CI: 0.9–56.7] (p = 0.037) for ATM." (PMID 39684352, 2024). "While there is evidence for association between variants in ATM or CHEK2 and multiple cancer types, the associations have not been consistently evaluated across all cancer types and, with the exception of breast cancer, the strengths of association are unclear." (PMID 39209703, 2024). "Correspondingly, bisulfite pyrosequencing was used to analyze DNA methylation at two ataxia telangiectasia mutated (ATM) gene loci in leukocytes, suggesting that ATM methylation could be a marker for breast cancer risk." (PMID 39273460, 2024). "ATM and PALB2 are two of the main breast cancer susceptibility genes." (PMID 39518003, 2024). "Studies to date do not show a significantly increased risk of contralateral breast cancer for women with breast cancer and at ATM mutation." (PMID 39543654, 2024). "From previous studies, the prevalence of ATM P/LP variants among non-BRCA mutated breast cancer patients varied widely." (PMID 38355628, 2024). "It is not yet clear how the identification of an ATM mutation in a patient newly diagnosed with breast cancer should impact on her treatment and follow-up." (PMID 39543654, 2024). "Oophorectomy has been shown to diminish breast cancer mortality in carriers of BRCA1, BRCA2 and CHEK2 mutation mutations but has not yet been studied in breast cancer patients with ATM mutations." (PMID 39543654, 2024). "Germline pathogenic variants (PVs) in ATM, BRCA1, BRCA2, CHEK2, and PALB2 are detected in 5-7% of unselected women with breast cancer in the general population and are associated with a significantly increased risk of breast cancer in unaffected women." (PMID 39624521, 2024). "Considering breast cancer-associated mutations across a broader range of genes (BRCA1, BRCA2, PALB2, and the more moderate-risk genes, ATM and CHEK2), the average carrier risk is equivalent to the top 3% of the PRS distribution (see S1 File for definition of mutation carriers)." (PMID 39292644, 2024). "The available findings do not display a significantly elevated risk of contralateral breast cancer among carriers of ATM pathogenic variants in comparison to non-carriers." (PMID 38397209, 2024). "Variants in the ataxia telangiectasia mutated gene ATM can increase the risk of breast cancer, though the gene is not on the ACMG v3.2 list of recommendations for reporting secondary findings in clinical exome and genome sequencing." (PMID 39438716, 2024). "Our results support the inclusion of ATM into the breast cancer gene panel for the Thai population." (PMID 38355628, 2024). "This variant of MSH gene was not described in any database, while this ATM variant was observed in individuals with breast and colon cancers and in a breast cancer study." (PMID 39673085, 2024). "GPVs in ATM and CHEK2 confer a moderate risk of breast cancer." (PMID 37258796, 2023).
breast cancer (continued). "One case with RAD51C duplication was found to carry the ATM c.7570G>C (p.Ala2524Pro) allele, recently established to confer a high-risk for breast cancer, whereas the rest had no other known moderate-to-high risk predisposing alleles." (PMID 37578974, 2023). "This is in line with findings in moderate breast cancer risk genes such as CHEK2, PALB2 and ATM and suggests that PRS inclusion in risk stratification may in particular be relevant to prevent excess of surveillance measures in PV carriers of those genes." (PMID 36872334, 2023). "Canonical breast-cancer-associated genes with pathogenic germline mutations were CHEK2 and ATM." (PMID 37239898, 2023). "Among participants with family history of breast cancer, PTVs in ATM (p-value = 0.002), BRCA2 (p-value = 0.005), BRCA1 (p-value = 0.046), PALB2 (p-value = 0.039) and RAD50 (p-value = 0.044) were significantly associated with increased risk of breast cancer." (PMID 37790698, 2023). "Recently published studies assessing the clinical validity of genes frequently tested in hereditary breast and ovarian cancer mostly agree that ATM, BRCA1, BRCA2, CHEK2, and PALB2 are strongly associated with a risk of breast cancer (overall with a p value of less than 0.0001)." (PMID 37239898, 2023). "In this sub-group, age at breast cancer diagnosis was no longer a significant predictor of mutation status for ATM (OR 1.12, 95% CI 0.97–1.30) and PALB2 remained non-significant (OR 1.05, 95% CI 0.90–1.23)." (PMID 37084156, 2023). "The involvement of ATM in breast cancer extends beyond its role in DNA repair." (PMID 38327652, 2023). "Breast cancer family history was not strongly associated with CHEK2 or ATM PV status among unaffected women." (PMID 37084156, 2023). "Overall, these data provide some of the first evidence for divergences in the causal impact of ATM, CHK2, and ATR inactivation on the type of breast cancer a patient develops and on disease progression, i.e., metastatic potential and responsiveness to endocrine therapies." (PMID 37390209, 2023). "For those with ATM 32% had breast cancer, 3.6% had endometrial cancer, and 14.3% had colon cancer." (PMID 35040284, 2022). "Germline mutations in PALB2, ATM, and CHEK2 are also associated with breast cancer risks as high as those associated with BRCA1/2 mutations and are often referred to as BRCA-like breast cancer." (PMID 35884530, 2022). "estimated an odds ratio (OR) of breast cancer risk of 2.1 (95% confidence interval (CI) 1.35–3.23, p < 0.001) for ATM pathogenic variant carriers compared to non-carriers." (PMID 35365198, 2022). "For example, the ATM carrier patients are more prone to develop subcutaneous necrosis and contralateral breast cancer after radiotherapy, which may be a relative contraindication to the standard management." (PMID 35681739, 2022). "For example, if a 20-year-old woman has a first degree relative with breast cancer and an ATM pathogenic variant, and her own test is negative, her risk is still raised above the population." (PMID 35190596, 2022). "A recent large American-based study of germline genetic testing criteria in 3907 women with breast cancer, identified 43 ATM variants, but did not distinguish between women with ductal and lobular cancers." (PMID 33763779, 2022).
breast cancer (continued). "Germline PV of other genes of the HR, especially PALB2, CHEK2, and ATM, were found in 0.5–1.5% of patients with unselected breast cancers, and were obviously more frequent among patients with family breast cancer history." (PMID 35158866, 2022). "Currently, approximately 40% of familial breast cancer risk is explained by a combination of common low-penetrance variants, together with coding rarer variants in predisposition genes, such as BRCA1, BRCA2, PALB2, ATM, and CHEK2 that confer higher risks." (PMID 35884425, 2022). "For women with other HOC mutations associated with significant breast cancer risk such as CHEK2, PALB2 and ATM, the impact of RRBSO on breast cancer risk remains unknown." (PMID 35159349, 2022). "Additionally, a previous study examined the role of ATM in cancer cell migration and metastasis in breast cancer cells." (PMID 36233063, 2022). "Using the breast cancer study as an example, it was found that the known eight famous genes—BRCA1, BRCA2, PALB2, BARD1, RAD51C, RAD51D, and ATM—in breast cancer research and practice actually lead to very low accuracy in predicting breast cancer status at the stage of diagnosis." (PMID 36298522, 2022). "Notably, among young patients diagnosed with breast cancer below the age of 30, approximately 25% of them carried BRCA2 deleterious mutations and 6.2% of them harbored ATM mutations, significantly higher than in women diagnosed ≥ 40 years (P=0.002)." (PMID 35494038, 2022). "However, other contributing factors for this association need to be investigated such as defects in homologous recombination (e.g., BRCA1, BRCA2, PALB2, ATM, CHEK2) known to increase risk of breast cancer." (PMID 36421330, 2022). "The use of KU-60019, an inhibitor of ATM, could increase the sensitivity of PTEN -deficient breast cancer cells to DDP." (PMID 35303867, 2022). "Hypermethylation of the promoters of tumor suppressor genes ATM, NOTCH1, NUP98, PALB2, TSC2, and WRN had all previously been associated with WTC exposure and were again observed to be hypermethylated in WTC EHC compared to NYUWHS breast cancer patients." (PMID 35564499, 2022). "In addition, more frequent, but less penetrant germline mutations have been identified in families with breast cancer in genes such as CHEK2, ATM, PALB2, and BRIP1." (PMID 35333900, 2022). "The underlying mechanism of increased cytotoxicity by combined EZH2/ATM inhibition in BRCA1-deficient breast cancer cells is not clear." (PMID 35715861, 2022). "To investigate the cytotoxic effect of combined EZH2 and ATM inhibition in human BRCA1-mutant breast cancer, we treated the human TNBC cell lines SUM149 (BRCA1-mutant) and CAL120 (BRCA1-wild type) with GSK126 and AZD1390, and analyzed cell viability using CellTiter-Glo and clonogenic survival." (PMID 35715861, 2022). "PARP-1 can also recruit protein MRE11, ATM (ataxiatel angiectasia mutated) to suppress the transcription factors E2F4 and P130 complexes and impact the expression of breast cancer susceptibility genes BRCA1 and RAD5, which transiently protects the DNA gaps and inhibits recombinant." (PMID 36590386, 2022). "Women who meet genetic testing criteria due to a personal or family history of breast cancer and are heterozygous carriers of a pathogenic variant in ATM have been estimated to be at a two–fourfold increase in breast cancer risk compared to non-carriers." (PMID 35365198, 2022).
breast cancer (continued). "Another study showed that ATM depletion sensitizes breast cancer cell lines to the PARPI olaparib." (PMID 35785170, 2022). "To avoid potential selection bias due to long-term deletion of Atm, we generated 4T1 mouse mammary carcinoma cells with doxycycline inducible expression of shRNA targeting either Atm, leading to ATM depletion within 4 days as confirmed by immunoblot analysis, or a non-target control." (PMID 35721517, 2022). "Besides, a recent large population study showed that other pathogenic gene variants, including ataxia telangiectasia-mutated (ATM) variants, were frequently detected among breast cancer women." (PMID 33402103, 2021). "The results of Egger’s test showed no publication bias in the association between ATM and risk of breast cancer in unadjusted case control studies (Coefficient: 0.398; P: 0.193; % 95 CI: − 0.21 – 1.00)." (PMID 33402103, 2021). "Indeed, irradiated breast cancer cells can release EVs able to activate checkpoint kinase 1 (Chk1), histone H2AX, and ataxia telangiectasia mutated (ATM) in recipient cells, thus triggering DNA repair responses." (PMID 33670185, 2021). "Two germline mutations were detected only in the older breast cancer patients but not in their younger counterparts: ATM [2/61; 3%] and APC [1/61; 1,6%] pathogenic mutations." (PMID 35127508, 2021). "Despite a growing recognition of the role of rare missense variants in cancer predisposition, especially in breast cancer and for genes such as CHEK2 and ATM, missense variants individually are currently most commonly classified clinically as variants of uncertain significance." (PMID 33804961, 2021). "The pooled prevalence of ATM in patients with breast cancer in several continent was 7% (95% CI: 5−8%; I square: 98%; P: 0.00), 5% (95% CI: 1−11%; I square: 80%; P: 0.01) and 9% (95% CI: 4−14%; I square: 96%; P: 0.00) for European, Asian and American population, respectively." (PMID 34493284, 2021). "In general, the ATM gene is involved in cell cycle control, apoptosis, gene regulation, oxidative stress, and telomere maintenance and is deregulated in many malignancies such as breast cancer (BC)." (PMID 34068084, 2021). "Our results may support this latter study and suggest that there is a acumulative effect of ATM and BRCA1 mutations that increase the risk of breast cancer incidence." (PMID 34493284, 2021).
breast cancer (continued). "ATM variants were highest in breast cancer patients from the USA,t but these variants were not involved in the prevalence of patients from northern Europe (Finland, Denmark, and Sweden)." (PMID 34493284, 2021). "We classified our data into BRCA positive and BRCA negative groups for identifying the association of ATM variants with BRCA1/2 mutation in breast cancer patients." (PMID 34493284, 2021). "For instance, in breast cancer cells, ATM expression can be reduced due to miRNA-18a." (PMID 34070860, 2021). "Still,the exact prevalence of ATM mutations in breast cancer is unclear, and there is no systematic review on the prevalence of ATM variants in breast cancer." (PMID 34493284, 2021). "Indeed, in breast cancer patients with variants such as in BRCA1, BRCA2, and ATM, it is recommended that the contralateral breast dose in mammography and radiotherapy be minimized in order to prevent secondary carcinogenesis." (PMID 34608183, 2021). "Our results suggest that breast cancers among carriers of PVs in ATM and CHEK2, which are relatively common and more typically ER/PR-positive, may behave similarly to those of women testing negative for germline PVs." (PMID 33426465, 2021). "This variant, which results in absent ATM protein expression, has been found in homozygous and compound heterozygous AT, and it has been associated with an increased breast cancer risk in heterozygotes." (PMID 34262154, 2021). "Three genetic factors are involved in breast cancer progression: high penetrance genetic mutations such as those in the BRCA1 and BRCA2 genes, intermediate penetrance variants such as those in ATM, BARD1, PALB2, and CHECK2 genes, and low-penetrance variants such as SNPs." (PMID 34493284, 2021). "The enrichment for breast cancer in non-Roma is due to variants with increased allele frequencies in ATM, BRCA2, and NQO2 genes." (PMID 34220960, 2021). "The heatmaps of the 10 HR−/HER2+ breast cancers were homogeneous, while for 9 HR-/HER2− cases, a major cluster with ATM, FGFR1, and WT1 frameshift mutations (n = 6 for ATM1, FGFR1 and n = 5 for WT1) and a minor one with JAK3 splice site mutations were prominent (n = 3)." (PMID 34203389, 2021). "In addition, two patients harbored a PV in a PDAC-predisposition and another gene: ATM/FANCE (PDAC patient with colon cancer) and BRCA2/CHEK2 (early-onset breast cancer PDAC patient)." (PMID 34503238, 2021). "In some studies, the ATM mutation (causing Ataxia Telangiectasia) was reported as a risk factor for breast cancer patients who did not have a BRCA1/2 mutation." (PMID 34493284, 2021). "It seems that deletion and insertion in ATM genes are infrequent in breast cancer patients." (PMID 34493284, 2021). "Furthermore, a frameshift deletion in exon 28 of the ATM gene was reported in this article in one breast cancer patient (among 192 patients) that produce a truncated protein." (PMID 34493284, 2021). "Studies have shown that timosaponin AIII can induce the apoptosis of a variety of tumor cells, such as breast cancer and colorectal cancer cells, by activating the ATM/Chk2 and p38 MAPK signaling pathways, inducing autophagy, activating Caspase-4/9, and blocking the cell cycle." (PMID 34202717, 2021). "miR-203 is a dominant indicator of downregulation of the ATM gene in breast cancer." (PMID 34198652, 2021).